CXCL1 (C-X-C motif chemokine ligand 1)
Diseases named in the same sentence as CXCL1 in open-access papers (continued):
Sharing a sentence is not in itself a finding about the gene and the disease.
breast carcinoma (continued). "Thus, TAMs/CXCL1 may be promising therapeutic targets for inhibiting breast cancer metastasis to the lungs." (PMID 30158589, 2018). "Thus, CXCL1 is closely correlated with breast cancer metastasis and survival." (PMID 30158589, 2018). "Finally, aggressive breast cancer cells stimulate secretion of CXCL1, 6 and 8 from MSCs." (PMID 29262555, 2017). "Overall, our study provides experimental evidence and molecular mechanisms that may facilitate the safe and effective use of herbal medicine for the prevention of breast cancer growth or metastasis, and may lead to CXCL-1-based therapeutic strategies for mammary malignancies." (PMID 29109519, 2017). "Interestingly, breast cancer treatment with chemotherapeutic agents has been found to increase CAEC-derived production of tumor necrosis factor (TNF)-alpha, causing an increase in production of CXCL1/2 via nuclear factor (NF)-kappaB by the cancer cells." (PMID 27515302, 2016). "Their activities have been reported in breast cancer and could affect CXCL1 transcript levels." (PMID 25344051, 2014). "Next, we confirmed that macrophage-derived CXCL1/2 and CFB were upregulated in tumors, liver and lung tissues, as well as serum from mice orthotopically inoculated with 4T1 breast cancer cells after Dox treatment by immunofluorescence staining and ELISAs." (PMID 41480760, 2026). "Together, these data suggest that macrophage-derived CXCL1/2 and CFB serve as key drivers of neutrophil aggregation and NET formation in breast cancer following chemotherapy and radiotherapy." (PMID 41480760, 2026). "High CXCL1/IL8 expression correlates with reduced NK cell infiltration and shorter distant-metastasis-free survival in breast cancer patients." (PMID 42185071, 2026). "In this study, Yang and colleagues also demonstrated that silencing CXCL1 or blocking IGF1R/STAT3 signaling disrupts this HMGB1–autophagy–MRPs axis and restores drug sensitivity in breast cancer." (PMID 41465435, 2025). "In breast cancer, MET signaling activates the MAPK pathway and promotes the release of inflammatory cytokines such as IL-1β, IL-8, and CXCL1, thereby reshaping the brain microenvironment and enhancing brain metastasis." (PMID 40860829, 2025). "While CXCL1 is highly expressed in several triple negative breast cancer cell lines, CXCR2 expression is reported to be reduced compared to other breast cancer subtypes." (PMID 40108668, 2025). "We noted elevated pro-inflammatory activity interactions, specifically with CXCL1, CXCL2, and CXCL8 in primary breast cancer." (PMID 40858590, 2025). "TAMs release C-X-C motif chemokine ligand 1 (CXCL1), which is involved in the activation of epithelial-mesenchymal transition (EMT) and promotes the migration and invasion of aggressive breast cancer cells." (PMID 41348904, 2025). "Their recruitment to the TME, mediated by chemokines such as CXCL1 and CXCL8, and their subsequent activation underscore their complex role in breast cancer biology." (PMID 40486614, 2025). "Endocrine-resistant breast cancer (ERBC) cells secrete CXCL1, which links with the CXCR1/2 on fibroblasts, activating ERK/MAPK signaling and inducing CXCL1 amplification." (PMID 40244377, 2025). "Silencing CXCL1 and CXCL2 downregulates multiple metastasis-promoting genes and inhibits the metastatic potential of breast cancer cells." (PMID 41378129, 2025). "Specific examples include the Aiduqing formula, which inhibits the expression and secretion of CXCL1 by TAMs, thereby inhibiting the chemotaxis and differentiation of initial CD4+ T cells to Tregs as a means to inhibit breast cancer metastasis." (PMID 40242756, 2025). "Conversely, CXCL1 knockdown in TAMs markedly suppressed TAM-induced chemoresistance, which was reversed upon the addition of CXCL1 cytokine in both breast cancer cell lines." (PMID 39394189, 2024).
breast carcinoma (continued). "In this study, using four established endocrine resistant breast cancer (ERBC) cell lines, we characterized CXCL1 as a secreted factor in crosstalk between ERBC cells and fibroblasts." (PMID 38393465, 2024). "Clinically, CXCL1 was shown to be an independent predictor of poor prognosis and to be positively correlated with IGF1R/STAT3/HMGB1 expression in breast cancer." (PMID 39394189, 2024). "Our previous study showed that BHS inhibits breast cancer growth and metastasis by suppressing TAM/CXCL1‐induced self‐renewal of CSCs." (PMID 39051750, 2024). "CXCL1 elevation in breast stroma usually predicts poor OS and recurrence-free survival (RFS) of patients with breast cancer." (PMID 38654356, 2024). "CXCL1 represents one of the most abundant chemokines in the TME, and its level in mammary tumor tissue tends to be increased compared to that in normal breast tissue." (PMID 38654356, 2024). "CCL20-regulated PMN-MDSCs secrete large amounts of CXCL1 by binding to CXCR2 and activating the NOTCH1/HEY2 signaling pathway in BC cells, leading to an increase in breast cancer stem cells (BCSCs)." (PMID 38609997, 2024). "The expression of the receptor for CXCL1, i.e., CXCR2, is lower in triple-negative breast cancer compared to other breast cancer subtypes." (PMID 37108425, 2023). "Only changes in five analytes (CXCL5, CXCL1, CCL17, CXCL10, and IL-6) were seen to overlap across all four breast cancer cell-line EV-stimulated conditions." (PMID 37441083, 2023). "Breast cancer cells secrete CXCL1 and CXCL8/IL-8, resulting in the chemotaxis of neutrophils into breast cancer cells." (PMID 37108425, 2023). "Transcriptomic data from TEPA treated breast cancer cells also displays changes in the immune-related genes (including IL6, IL6R, IL15, CXCL1, CXCL8, and PTX3) in breast cancer." (PMID 37480151, 2023). "In lung fibroblasts, CXCL1, as well as other CXCR2 ligands, increases the expression of CCL2/MCP-1 and CCL7/MCP-3, both of which increase cholesterol synthesis in breast cancer cells in the lung." (PMID 37108425, 2023). "This article summarizes existing knowledge about the roles of CXCL ELR-positive chemokines CXCL1, CXCL2, CXCL3, CXCL5, CXCL6, CXCL7, and CXCL8 as peripheral blood and tissue markers in the diagnosis and prognosis of women with breast cancer." (PMID 37370728, 2023). "This kinase inhibits nuclear factor κB (NF-κB) activation and thus downregulates CXCL1 expression in MCF-7 cells and other breast cancer cell lines." (PMID 37108425, 2023). "The simultaneous expression of CXCL1 and the receptor for this chemokine, CXCR2, allows breast cancer stem cells to act on themselves in an autocrine manner." (PMID 37108425, 2023). "IL-17 can upregulate the expression of CXCL1 in breast cancer cells, thereby activating the AKT/NF-κB signaling pathway and promoting the growth and metastasis of breast cancer." (PMID 37138170, 2023). "Using a cytokine array, osteocyte-derived CXCL1 and CXCL2 cytokines were identified as regulators of migrating breast cancer cells." (PMID 37174109, 2023). "CXCL1, CXCL2, CXCL8, and CXCL12 were observed to diminish tumor response to chemotherapy, especially in breast cancers." (PMID 36612163, 2022). "A study in breast cancer treatment found that cancer-associated endothelial cells contribute to the production of CXCL1/2 and S100A8/9, which eventually led to breast cancer cell survival and drug resistance." (PMID 36389798, 2022). "Our RNA-seq results showed that the expression of CXCL1, CXCL2, CXCL3, and CXCL8 was significantly increased in breast cancer cells after co-culturing with adipocytes." (PMID 35280694, 2022). "CXCL1 and CXCL8 belong to the ELR-motif-containing group of CXC chemokines, which, in breast cancer (BC), stimulate angiogenesis and increase migration and invasiveness of tumor cells." (PMID 36431173, 2022). "Breast cancer cell-derived CXCL1/2 recruits MDSCs to produce S100A8/9, thus augmenting the metastatic tendency of breast cancer cells." (PMID 36612163, 2022).
breast carcinoma (continued). "Our cytokine array showed that other cytokines such as CXCL1 and IL32-alpha are downregulated upon SHP2 inhibition in breast cancer cell lines." (PMID 35739379, 2022). "An abnormal expression of CXCL1 and CXCL8 has been found in many types of malignancies, including breast cancer." (PMID 36431173, 2022). "As tumor-promoting proteins that are expected to be downregulated in osteocyte-derived CM, we focused on the expression levels of CXCL1, and CXCL5, two chemokines that are involved in the migration of breast cancer cells." (PMID 33802279, 2021). "Herein, we demonstrated that ADQ exhibited no detectable side effects in vivo, while it remarkably suppressed breast cancer immune escape and lung metastasis by suppressing the TAM/CXCL1/Treg pathway." (PMID 34461944, 2021). "Lastly, mouse 4T1-Luc xenograft experiments validated that ADQ formula inhibited breast cancer immune escape and lung metastasis by suppressing the TAM/CXCL1/Treg pathway." (PMID 34461944, 2021). "Through inhibition of CXCL-1 and CXCL-2, curcumin diminished the formation of breast cancer lung metastases." (PMID 34948368, 2021). "Three angiostatic peptides, identified through the same methodology and derived from either type IV collagen, CXCL1, or a thrombospondin domain-containing protein were tested in an in vivo MDA-MB-231 breast cancer model." (PMID 34503058, 2021). "Although CXCL1 has been shown to be involved in BC progression and chemotherapy resistance, the question of whether it has a role in breast cancer stem cell (BCSC) behavior, which is the cornerstone of metastasis and resistance to chemotherapy, has never been addressed." (PMID 34195201, 2021). "Out of 12 CXCL chemokines, we found that the expression of CXCL8, CXCL1, and CXCL2 transcripts was significantly elevated in ER- breast cancer specimens compared to ER+ samples in seven, four and three independent studies, respectively." (PMID 33912188, 2021). "A number of studies have revealed that CXCL1 expression elevation in breast stroma usually predicts poor OS and recurrence-free survival (RFS) of breast cancer patients." (PMID 34461944, 2021). "We found that nine genes were differentially expressed in breast cancer versus normal tissues (CXCL9, 10, 11, and 13 were up-regulated, and CXCL1, 2, 3, 12, and 14 were downregulated)." (PMID 34439306, 2021). "In another model of murine breast cancer, MMTV−Neu (Mouse Mammary Tumor Virus—Neu oncogene), we observed an increase of Cxcl1, Cxcl2, Cxcl3, and Cxcl5 levels in the tumor of MMTV−Neu animals compared to the mammary gland of WT animals." (PMID 34070438, 2021). "Curcumin monotherapy upregulated miR181b and downregulated miR181b targets, CXCL-1 and CXCL-2, in cells isolated from primary human breast cancers and MDA-MB-231 cells." (PMID 34948368, 2021). "In summary, ADQ can suppress breast cancer immune escape and lung metastasis by blocking the TAM/CXCL1/Treg pathway." (PMID 34461944, 2021). "To date, key roles were identified in breast cancer for CXCR1/CXCR2 and their CXCL1/CXCL8 ligands in promoting resistance to chemotherapeutic drugs such as doxorubicin and paclitaxel." (PMID 32582148, 2020). "CXCL1 can promote breast cancer migration and invasion ability, as well as EMT in both mouse and human breast cancer cells." (PMID 33123472, 2020). "In EO771 mammary carcinoma cells, knockdown of PLAC1 resulted in the reduced expression of several inflammatory and immune factors, including Cxcl1, Ccl5, Ly6a/Sca-1, Ly6c, and leukemia inhibitory factor." (PMID 32499871, 2020). "After CXCL1 treatment, SOX4 expression significantly increases in the nucleus of various breast cancer cell lines." (PMID 33123472, 2020). "Not only does the future metastatic organ express high levels of CXCL1, but its chemokine receptors CXCR4 and CCR7 are also highly expressed in human breast cancer cells." (PMID 32079335, 2020).
breast carcinoma (continued). "Another chemokine, of which secretion was elevated by AgNPs treatment, was CXCL-1 that promotes breast cancer migration and its invasive capacity, as well as EMT in human breast cancer cells and in vivo animal models." (PMID 32443890, 2020). "ELR+ CXC chemokines such as CXCL1 and CXCL8, as well as their CXCR1/CXCR2 receptors, have been demonstrated to be significant factors in promoting CSC enrichment in breast cancer." (PMID 32582148, 2020). "In summary, CXCL1 expression and secretion induced in V-THP-1 contributed to the malignancy of breast cancer cells and positively correlated with ERK phosphorylation in the visfatin-TAMs-CXCL1 axis." (PMID 33256011, 2020). "Taken together, our study provided preclinical evidence supporting the application of XIAOPI formula in preventing breast cancer PMN formation, and highlighted TAMs/CXCL1 as a potential therapeutic strategy for PMN targeting therapy." (PMID 32213179, 2020). "Our study not only provided evidence supporting the application of XIAOPI formula in preventing breast cancer PMN formation, but also highlighted the critical role of TAMs/CXCL1 as a potential therapeutic target in preventing breast cancer metastasis." (PMID 32213179, 2020). "CXCR2, the receptor for CXCL1, provides one such therapeutic strategy with CXCR2 inhibitors such as Repertaxin currently in Phase II clinical trials in breast cancer." (PMID 33256011, 2020). "Increased CXCR2 and its ligands CXCL1, CXCL5, and CXCL7 were found in co-cultured MSCs and breast cancer, with this axis augmenting breast cancer cell migration." (PMID 31130595, 2019). "Bone marrow-derived mesenchymal stem cells (MSCs) express CXCL1 and CXCL5 to recruit PyMT breast cancer cells and prompt the migration in a CXCR2-dependent manner in vitro." (PMID 31788042, 2019). "CXCR2 affects angiogenesis in breast cancer primarily by interacting with CXCL8 and CXCL1, however the specific mechanism is yet to be determined." (PMID 31788042, 2019). "In breast cancer models, IL17 is found to increase the secretion of CXCL1 and CXCL5 by mammary carcinoma cells, which further facilitates cancer progression." (PMID 31010242, 2019). "Thus, CXCL1 might be a mediator of breast cancer metastasis." (PMID 30158589, 2018). "We also used immunofluorescence to determine the effects of CXCL1 on SOX4 signaling, and found that after CXCL1 treatment, SOX4 expression significantly increased in the nucleus of both breast cancer cell lines." (PMID 30158589, 2018). "Taken together, using meta-analysis that combines gene set and network analysis, we suggested CXCR4, CXCL1 and HMGCS1 as candidates involved in tumor stem-like breast cancer cells." (PMID 26870956, 2016). "Previous studies have shown that CAFs production of CXCL1, CXCL2, PTGS2/COX-2, and IL-6 in breast cancer can modulate the functions of immune cells in TME." (PMID 26884644, 2016). "Here, we used a combination of siRNA and pharmacologic approaches to demonstrate that key factors expressed in breast cancer, TGF-β and HGF, modulate CXCL1 expression in CAFs." (PMID 26252654, 2015). "We had previously demonstrated that the murine CAF lines 41CAFs and 83CAFs, expressed higher levels of CXCL1 expression and lower levels of TGF-β compared to normal mammary fibroblasts (311NAF), similar to expression patterns of human breast cancer stroma." (PMID 26252654, 2015). "In summary, these data indicate CXCL1 is expressed in both α-SMA and FSP1 positive fibroblasts in breast cancer stroma." (PMID 25344051, 2014). "We have described previously in the context of bone metastasis induced by breast cancer cells that LPA through LPA1 controls the expression of IL6, IL-8, CSF2(GM-CSF), and CXCL1(Groα)." (PMID 24828490, 2014). "In summary, we provide insight into the clinical significance of stromal derived CXCL1 expression, and show that α-SMA and FSP1 positive CAFs in breast cancer stroma are sources of CXCL1 expression." (PMID 25344051, 2014).
breast carcinoma (continued). "In this report we provide novel data showing that macrophages from SEMA7A shRNA knockdown mammary tumor bearers have decreased production of angiogenic chemokines CXCL2/MIP-2 and CXCL1 as well as matrix degrading enzyme, MMP-9." (PMID 24550834, 2014). "It has been shown that TGF-β inhibited TNF-α-induced CXCL1 release in human ECs and TGF-β regulated suppression of inflammatory genes such as CXCL1 and CXCL5 in mammary carcinoma cells." (PMID 23665907, 2013). "For example, SNAI1 transcribes CXCL1 and CXCL2 to regulate MDSCs infiltration in breast cancer." (PMID 41280721, 2025). "The reason may be that CXCR2 activation can be affected by not only IL-8 signaling but also CXCL1 signaling, indicating that CXCR2 is the key target through which depression promotes the progression of breast cancer." (PMID 40839237, 2025). "Furthermore, the XIAOPI formula promotes chemosensitivity to Taxol treatment by inhibiting the CXCL1/HMGB1-mediated autophagy axis, diminishing survival pathways in breast cancer-resistant cells." (PMID 41465435, 2025). "Similarly, CXCL1 expression is reduced by tumor cell-derived SPTBN1 and further inhibits macrophage polarization in breast cancer." (PMID 39858015, 2025). "Moreover, the exogenous addition of CXCL1‐overexpressing EV‐Apo (EV‐AporCXCL1, 200 μg/20 g, q3d) strongly reversed the synergistic inhibition effect between BHS and paclitaxel on breast cancer growth and lung metastasis." (PMID 39051750, 2024). "In addition, medium produced in vitro by the EPS of human muscle cells and a combination of recombinant myokines CXCL1, IL10, and CCL4 also reduced the growth rate and induced cell death of breast cancer cells." (PMID 39518934, 2024). "Both CXCL1 knockdown in EV-dead and macrophage depletion partially inhibited the promotion effect of EV-dead on TNBC growth and lung metastasis in the mouse 4 T1-Luc xenograft model, leading to the increased OS of the mammary tumor-bearing mice." (PMID 38654356, 2024). "Finally, the activation of mGluR1 in MDA-MB-231 breast cancer cells can release the cytokines and chemokines (CXCL1, IL6, IL8) that activate the immune-suppressive immune cell promoting the malignant transformation of breast cancer cells." (PMID 36817470, 2023). "Bioinformatics analysis of in silico publicly available TNBC data identified BCL3 and BCL2 as well as the following anti-tumour immune response biomarkers as significantly altered in TNBC compared to other breast cancer subtypes: GZMA, PRF1, CXCL1, CCL2, CCL4, and CCL5." (PMID 38022682, 2023). "CXCL1 (C-X-C motif chemokine ligand 1) was the most abundant chemokine secreted by TAMs, and CXCL1 could promote migration, invasion ability, and EMT in breast cancer." (PMID 37770991, 2023). "In addition, the secretion of CXCL1 and CXCL5, two cytokines involved in breast cancer metastasis, was moderately increased in all subgroups after indirect co-culture with MDA-MB-231 cells." (PMID 36710348, 2023). "In our own study, we did not compare the CXCL1 plasma concentrations between luminal breast cancer patients and healthy women." (PMID 37370728, 2023). "The action of sex hormones plays an important role in the development of breast cancer—no less important are cytokines, including CXCL1." (PMID 37108425, 2023). "This is also supported by the observation that the expression of AREG and CXCL1 did not correlate in breast cancer, while they highly correlated in prostate cancer." (PMID 35998057, 2022). "Thus, similar to our observations in the PDX models, it seems that while most patients exhibit a low to medium expression of CXCL1, CSF2, and IL-1β, a fraction of breast cancer patients exhibit high expression levels of these cytokines." (PMID 36551639, 2022). "The use of CXCL1 promoter inhibitors reduced the migration of breast cancer cells and the number of BCSCs, suggesting that TAMs may support BCSC survival by secreting CXCL1." (PMID 35740975, 2022).